IL4 (interleukin 4)
Diseases named in the same sentence as IL4 in open-access papers (continued):
Sharing a sentence is not in itself a finding about the gene and the disease.
tumor (continued). "Thus, IL-4 and TNFα, which could be released by immune cells of the tumor microenvironment, are able to control the B7-H1 expression in RCC thereby altering T cell responses." (PMID 24885059, 2014). "However, IL-4 plays a bilateral role in the control of tumor growth." (PMID 25484626, 2014). "Thus, blocking of IL-4 may affect T-cell-mediated tumor activity, which could lead to a skewed immune response toward T-cell effector responses." (PMID 25208941, 2014). "Similarly, dramatic effects are seen on tumor control following IL-4 ablation." (PMID 23991011, 2013). "Third, although the IL4 pathway was significantly enriched in both the tumor progression and chemotherapy signatures, the IL4 gene was not differentially expressed in either of the two comparisons, and the expression levels of two receptors for IL4 (IL4R and IL2RG) were divergent." (PMID 23451142, 2013). "Thus, the immune parameters in atopic disease (e.g.: IgE, TLR ligands, IL-4) may propel innate and adaptive immune responses toward tumor eradication." (PMID 22251275, 2012). "Therefore, IL-4 was added to wells containing primary naïve and tumor-educated BAL macrophages to determine if alternative activation could increase IGF-1 production in either macrophage group." (PMID 21699731, 2011). "For example, IL-4 is thought to directly inhibit proliferation of cells from cancers such as colon tumors, head and neck tumors, and glioblastomas, while in other cases it is thought to induce a host immune response against the tumor cells such as in B-cell lymphomas and melanomas." (PMID 20445741, 2010). "In addition to IL-4, other tumor-derived factors are likely to be involved in these events." (PMID 20167088, 2010). "IL-4 presents antiangiogenic properties which could inhibit the tumour growth." (PMID 20049171, 2009). "Various IL-4R-expressing tumour types may have different downstream mediators of IL-4 action." (PMID 15714203, 2005). "However, exogenous IL-4 has been shown to mediate contrasting effects on various tumour cell lines." (PMID 11870521, 2002). "The universal expression of gp200-MR6 in neoplastic and non-neoplastic urothelium has important implications for the possible use of IL-4 in tumour therapy and suggests that IL- 4 may play a role in differentiation and homeostasis of urothelium and other mucosal epithelia." (PMID 8595155, 1996). "IL-4-induced M2 macrophages were evaluated for ADAM9 expression, tumor migration and invasion capacity, extracellular matrix (ECM) degradation, cytoskeletal remodeling, and spheroid destabilization." (PMID 41890767, 2026). "IL-4-induced M2 macrophages upregulated ADAM9 and significantly enhanced tumor migration and invasion." (PMID 41890767, 2026). "Monocyte subsets 3 and 4 and MG1—the immune populations most enriched within tumor regions—received the strongest incoming signals via tumor-promoting networks such as galectin, complement, TGF-β, SPP1, TNF, and IL-4." (PMID 41503214, 2026). "In contrast, MG3, MG4, and monocyte subsets 1 and 2—which were less concentrated within tumor cores—exhibited significantly weaker engagement with pro-tumor or immunosuppressive pathways, including MIF, TNF, IL-4, IL-6, OSM, galectin, and TGF-β." (PMID 41503214, 2026). "Additional DE and PTM overlapping pathways, including HMGB1 signaling, the regulation of the epithelial–mesenchymal transition (EMT) by growth factors, and IL-4 and IL-13 signaling, indicated the broader impact of RONS on the tumor microenvironment." (PMID 39857768, 2025). "IL4, secreted by Th2 cells, binds to IL4R on tumor cells, leading to activation of signal transducer and activator of transcription 6 (STAT6) and the subsequent upregulation of GATA3 and IL4 expression." (PMID 39941924, 2025). "CD4 + Th cells modulate the tumor microenvironment by secreting cytokines such as IFN-γ, TGF-β, IL-4, IL-5, and IL-6." (PMID 40441260, 2025).
tumor (continued). "In an in vitro PDAC tumor setting, Cas9 + hdr treated Panc-1 cells resulted in decreased M2 TAM polarization, increased M1 TAM polarization, PD-L1 depletion inhibited M2 IL-4 secretion, and upregulated M1 TNF-αsecretion." (PMID 39958358, 2025). "They exert potent anti-tumor effects by secreting cytokines such as IFN-γ, IL-4, and TNF-α, engaging in direct cytotoxicity, and recruiting immune effectors like CD8+ T cells, DCs, and NK cells." (PMID 39941775, 2025). "Tumor-derived signals promote macrophage polarization toward a pro-tumoral M2-like phenotype, supported by IL-4, IL-13, IL-10, TGF-β, hypoxia, immune complexes and tumor metabolites." (PMID 41230456, 2025). "M2 expresses high levels of CD163, CD206, CCL18, and CCL22, releasing anti-inflammatory (TGF-β, IL-4, and IL-13) and inflammatory (IL-6, IL-12, and TNF-α) factors, as well as tumor-promoting arginase-1 and VEGF, modulated by TME signals." (PMID 40940877, 2025). "Cytokines secreted by tumor cells and Th2 lymphocytes (such as IL-4, IL-10, and TGF-β) drive the polarization of TAMs toward the M2 phenotype, resulting in immune suppression and accelerated tumor development." (PMID 40843751, 2025). "Utilizing the Pdx-Cre;KRASLSLG12D model, the authors detected enriched IL4, STAT6 and MYC level in these tumor lesion, which are dramatically infiltrated by CD4 + T cells, potentially contributing to pancreatic cancer initiation and progression." (PMID 39806421, 2025). "Increased P2X7R expression was found to significantly correlate with the expression levels of 5 ‘tumour-promoting’ mediators – VEGFB, IL-4, MMP-9, PCNA and IL-8." (PMID 41034696, 2025). "In our co‐culture system, interleukin 4 (IL4), IL8, and IL10 levels were significantly increased in the medium from THP‐1 macrophages co‐cultured with tumor cells overexpressing ITGβ8, which indicates that more macrophages exhibited the M2 phenotype." (PMID 39535362, 2025). "Antigen pulsing was performed by culturing the mDCs in the presence of cytokines rh-IL-4, rh-GMC-SF, rh-IL-6, rh-IL1b, rh-IL12, rh-IL-15, and rh-TNF-α and incubating 106 cells with 18 μg of tumor lysate or cultured cell lysate for 18 h." (PMID 40733726, 2025). "CD4+ T cell subsets, particularly Th2 and Th17, contribute to tumor progression by promoting TAM and MDSC recruitment via IL-4, IL-13, and IL-17-driven pathways." (PMID 40475782, 2025). "Priming CAR-T cells with IL-4 or incorporating IL-4 during CAR-T cell manufacturing improved their functional fitness and significantly prolonged tumor control." (PMID 39724176, 2025). "In contrast, GM/IL4-DCs contained fewer cDC subpopulations, eliciting a weaker initial CD8+ T cell response and yielding relatively inferior anti-tumor effects." (PMID 40977690, 2025). "Th1 cells release anti-tumor cytokines like interleukin (IL)-2, interferon (IFN)-γ, and tumor necrosis factor (TNF)-α, while Th2 cells release immunosuppressive IL-4, IL-5, IL-10, and IL-13." (PMID 40260236, 2025). "These inhibitors improve the CD8+ cytotoxic T cell to regulatory T cell (CD4+FOXP3+) ratio, modulate cytokine levels (including IL-4, IFN-γ, and TNF-α), and enhance the tumor immune microenvironment." (PMID 40573881, 2025). "As MF progresses, there is a decline in anti-tumor Th1 responses (e.g., IFN-γ, IL-12) and a predominance of Th2 cytokines such as IL-4, IL-5, and IL-13." (PMID 40864740, 2025). "In contrast, M2 polarization is driven by interleukin-4 (IL-4), interleukin-13 (IL-13), macrophage colony-stimulating factor (M-CSF), and transforming growth factor-β (TGF-β), contributing to pro-tumor characteristics." (PMID 40547026, 2025). "This reprogramming is mediated by Th2-skewing cytokines (e.g., IL-4, TGF-β1) and tumor-derived growth factors (e.g., CSF1, GM-CSF), fostering a microenvironment that supports tumor growth and metastasis." (PMID 40433363, 2025).
tumor (continued). "Moreover, co-incubation of exosomal GAS5 with CD4+ T cells inhibited their differentiation into an IFN-γ-producing Th1 phenotype, skewing it towards an IL-4-producing Th2 phenotype, in part by downregulating the transcription factor T-bet, which may promote tumor cell survival." (PMID 40429961, 2025). "On the other hand, M2-type TAMs secrete cytokines like IL-4, TGF-β, and M-CSF, facilitating tumor cell growth and participating in tumor infiltration, metastasis, and angiogenesis." (PMID 41041337, 2025). "We examined cytokine secretion profiles (IL-2, IL-4, IL-6, and IFNG) from activated T cells (CD69, IL-2RA, CD38, and HLA-DRB1) to evaluate T-cell activation in the CM tumor microenvironment, revealing consistently low expression levels." (PMID 40959090, 2025). "By suppressing T cell anti-tumor activity through the release of immune-suppressing proteins like IL-10 and IL-4, the M2-like TME promotes tumor growth by relying on oxidative phosphorylation (OXPHOS) and fatty acid oxidation (FAO)." (PMID 41451233, 2025). "Various cytokines produced by both tumor and stromal cells, such as GM-CSF, M-CSF, VEGF, IFN-γ, IL-4, IL-6, IL-13, and TGF-β, are involved in MDSC activation through STAT3 pathways." (PMID 40805183, 2025). "On the contrary, M2-TAMs create an immunosuppressive TME and favor tumor cells for invasion, metastasis, angiogenesis, and remodeling of the ECM by secreting high levels of anti-inflammatory cytokines such as interleukin IL-4, IL-13, and IL-10." (PMID 40805183, 2025). "They enhance anti-tumor immunity by secreting IFN-γ, IL-2, IL-4 and IL-17, which activate cytotoxic T lymphocytes (CTLs), natural killer (NK) cells, and macrophages." (PMID 40438115, 2025). "Their functional maturation is promoted by cytokines such as IL4, IL6, IL13, and TNF, while mobilization into the tumor niche is orchestrated by chemoattractants including IL8, CCL2, and CXCL12." (PMID 41155172, 2025). "TH2 cells secrete IL4, IL5, IL10, IL13, and IL17 - all of which have been shown to contribute to the tumor-promoting role of this subtype, even though IL4, IL5, and IL13 have been shown to contribute to the growth and metastasis of cancer." (PMID 41019045, 2025). "IL-4 can activate M2-type macrophages, secrete IL-10, TGF-β, and CCL17, thereby inhibiting T cell-mediated anti-tumor immune responses." (PMID 40557160, 2025). "Promotes IL-4 induced M2-like macrophage polarization via FXR in the liver, creates an immunosuppressive tumor microenvironment." (PMID 40458800, 2025). "elimination of CAFs increases the level of IL-2, IL-7, the number of dendritic and cytotoxic T cells with antitumor functions, and decreases the level of IL-4, IL-6, VEGF, the number of pro-tumor macrophages, and immunosuppressive T lymphocytes." (PMID 40136652, 2025). "IL-4 secreted within the TME binds to the IL-4 receptor on T cell surfaces, suppressing their activity and facilitating tumor immune escape." (PMID 40948749, 2025). "To assess anti-tumor activity, we analyzed the secretion of Th1 (IFN-γ) and Th2 (IL-4) cytokines from restimulated splenocytes." (PMID 40403026, 2025). "Furthermore, cytokines secreted by TH2 cells, including IL-4 and IL-13, stimulate lung mesenchymal stromal cells to upregulate C3 expression, which promotes neutrophil recruitment and the formation of extracellular traps, ultimately contributing to tumor metastasis." (PMID 40260250, 2025). "In some settings, IL-4 upregulates CD30 expression on activated CD4+ T cells, thereby increasing the density of BV targets on the tumor surface." (PMID 40864740, 2025). "The detected immune activation, highlighted by elevated cytokines (IFN-γ and IL-4) and enhanced CD8 + T cell infiltration, emphasizes this combination therapy’s potential to alter the tumor microenvironment." (PMID 40403026, 2025). "IL4 and IL4R can induce M2 macrophage polarization, thereby promoting tumor progression and metastasis." (PMID 40656893, 2025).
tumor (continued). "Meanwhile, we performed flow cytometry to quantify cytokine production in tumor-infiltrating γδ T cells, including IL-17, TNF-α, IFN-γ, IL-4, IL-10, and TGF-β." (PMID 41055972, 2025). "This alteration is characterized by increasing IFN-γ and decreasing IL-4 and TGF-β (P < 0.05), thereby promoting an anti-tumor Th1 immune response." (PMID 40417456, 2025). "In vivo, anidulafungin significantly increased serum levels of IFN-γ and IL-4 in tumor-bearing mice and elevated expression of IFN-γ and granzyme B (GZMB) in tumor tissues, confirming its immune-mediated anti-tumor effects." (PMID 40872601, 2025). "Anti-tumor response was indicated by a decreased number of lung nodules and enhanced expression of IFN-γ, IL-12 and IL-4 in splenocyte s." (PMID 41012179, 2025). "Among these, the key secretory molecules, IFN-γ, CXCL10, IL-4, VEGF, and TNF-α, are mainly involved in angiogenesis and tumor progression." (PMID 41029387, 2025). "Activated type I NKT cells release perforin/granzyme to induce tumor cell apoptosis, express FasL to initiate apoptosis via binding to tumor cell Fas, and secrete cytokines (IFN-γ, IL-4, tumor necrotic factor-α) to enhance NK/CD8+ T cell cytotoxicity." (PMID 41181157, 2025). "Increases M1 macrophages, enhances the expression of anti-tumor cytokines (IFN-γ, TNF-α, and IL-12), and reduces the level of pro-tumor cytokines (IL-10, IL-4, and TGF-β)." (PMID 38361933, 2024). "Tumor cells may acquire TFH-like and cell proliferation phenotypes during clonal evolution through CNV accumulation, including chr5 gain, consistent with the previously reported increased expression of T-cell activation-associated genes, including IL4, in cases with chr5 gain." (PMID 38012392, 2024). "Further, curcumin downregulated the gene expression of factors secreted by tumor cells known to induce immunosuppression (VEGFA, PDGF, IL4, OSM, CXCR4 and Fas ligand)." (PMID 39861845, 2024). "Specifically, fermented milk inhibited breast cancer cell proliferation, reduced tumor size, and modulated cytokines (downregulated IL-6 levels and upregulated TNF-α, IL-4, and IL-10 levels)." (PMID 39605907, 2024). "It is worth noting that while BMDMs were stimulated solely with purified IL-4 as a single stimulus, THP-1 cells were exposed to tumor-CM, which is a complex mixture of various stimuli." (PMID 39702544, 2024). "Among them, M2a is induced by IL-4/IL-13 and secretes IL1-Ra, arginase-1 (Arg-1), TGF-β, CCL17, and CCL18, which inhibit M1-TAM polarization and promote tumor cell growth and metastasis." (PMID 39560523, 2024). "Furthermore, IL-4 might influence the tumor cells’ resistance to radiotherapy and chemotherapy." (PMID 39207449, 2024). "The selection of cytokines was based on their significant role in regulating the tumor microenvironment, including promoting either the Th1 (IL-2RA, IL-12(p40), IL-15, TNF-α, IL-1β, IL-1RA, and IFN-γ) or the Th2 (IL-4, IL-6, IL-8, and IL-10) profile." (PMID 39768997, 2024). "Together, our results suggest that activated Th2 cells produce more IL-4, promote macrophage M2 polarization, and increase CD56 homodimers, thereby advancing tumor progression, especially in LIHC." (PMID 38560576, 2024). "HES1 expression was upregulated by IL-4, EGF, TGF-β, and other factors, consistent with earlier reports, including studies showing that tumor-CM contain Hes1-inducing factors." (PMID 39702544, 2024). "Pro-tumour cytokines such as vascular-endothelial growth factor α (VEGF-α) and the interleukins (IL) IL-4, IL-5, IL-6, IL-10, and IL-13 produced by T-helper (Th2) lymphocytes have also been linked to the pathogenesis of MCD." (PMID 40729293, 2024). "c-Myc directly regulates and replaces activation related genes, upregulates signaling mediators involved in IL4, and transcriptional activators STAS6 and PPARγ involved in the expression of tumor related macrophages." (PMID 39620221, 2024).
tumor (continued). "TCR-engineered CD8+ T cells secreted IL-2, IL-4, IL-6, and IL-10 when cocultured with KRASG12V tumor cell lines." (PMID 39287991, 2024). "Previous studies have mainly explored the biological function of M2-type macrophages driven by IL‐4 or IL‐13, and macrophages undergoing LAP also exhibit a tumour-promoting phenotype." (PMID 39756316, 2024). "The 16-biomarker panels were divided into three categories of inflammatory markers (SAA, CRP, NLR, PLR, and LDH), TH1/TH2 cytokines (IL-2, IL-4, IL-5, IL-6, IL-8, IL-10, IFNγ, TNF, and GM-CSF), and HCC tumor markers (AFP and PIVKA-II)." (PMID 38409200, 2024). "Only with simultaneous activation of the Vδ2 T cell TCR, which recognizes phosphoantigens on stressed, infected or tumor cells, did CAR-DAP10 signaling mount a full response with release of IFN-γ, TNF-α, IL-2, IL-4, GzmB and cytotoxicity against tumor cells." (PMID 39061247, 2024). "Significant inhibition of tumor growth was observed, along with differences in the levels of measured cytokines such as IL-2, TNF-α, IFN-γ, and IL-4." (PMID 39367471, 2024). "The production of local cytokines (including IL-4, IL-10, VEGF, and TGF β) promotes tumor growth and progress, and up-regulation of immune checkpoints also suppresses tumor immunity." (PMID 38664743, 2024). "In several types of solid tumors, the pathway signaling of IL-4/STAT6 pathway is used by M2a cells to promote cancer progression and stimulate the proliferation of tumor cells." (PMID 39796695, 2024). "The study also revealed that significant cell death can trigger cytokines like IL‐4, IL‐10, IL‐13, and TGF‐β, which aid in efferocytosis‐induced wound healing and further support the progression of metastatic tumours." (PMID 38501838, 2024). "TAMs secrete a series of cytokines and inflammatory factors such as TGF-β), IL-6, IL-10, IL-13, IL-4 and TNF-α that promote tumour initiation, growth, metastasis, angiogenesis, proliferation and chemoresistance in HCC (Ref." (PMID 39320855, 2024). "Multiplex immunofluorescence staining assays further revealed that IL-4 was well colocalization with cancer cell marker EpCAM and POSTN was mainly distributed in tumor stroma." (PMID 38773979, 2024). "Given the increase in pro-inflammatory CD4(+) T cells after oHSV treatment, we next analyzed IFN-γ, TNF-α, IL-4, IL-17A, and IL-21 intracellular expression within the CD4(+) tumor infiltrates." (PMID 38895115, 2024). "Cancer cells directly drive cholesterol efflux from macrophages and facilitate IL4-driven STAT6-dependent protumor TAM programming, while the deletion of ABC transporters reverts the tumor-promoting programming of TAMs." (PMID 39516356, 2024). "Blocking IL-4, which suppresses IL-12 production, in NSCLC mouse models augmented cytokine production by CD4+ T cells activated by mregDCs, resulting in reduced tumor growth and an increased expansion of IFNγ+TNF+CD8+ T cells." (PMID 38716077, 2024). "Our findings suggest that the crosstalk between CAFs and tumor cells via POSTN and IL-4 plays an important role in papillary thyroid tumor progression." (PMID 38773979, 2024). "High Il33 expression in tumor cells recruits and activates TH2 and ILC2 cells which secrete pro-tumorigenic cytokines such as Il4, Il5, and Il13." (PMID 38942797, 2024). "The influx of mast cells into TME is mediated by tumor-cell-released chemoattractants, such as SCF or CCL15, and then mast cells can actively participate in the elimination of tumor cells through secreted histamin, TNF-α, and IL-1, IL-4 and IL-6." (PMID 38287290, 2024). "Some of these molecules are transforming growth factor beta (TGF-B), interleukin-10 (IL-10), interleukin-4 (IL-4) and the onco-immunogenic molecule CD155 overexpressed in tumor microenvironments (TME), which all play multiple immunosuppressive roles." (PMID 39091493, 2024).